PIN1 (peptidylprolyl cis/trans isomerase, NIMA-interacting 1)
Diseases named in the same sentence as PIN1 in open-access papers (continued):
Sharing a sentence is not in itself a finding about the gene and the disease.
prostate carcinoma (33 papers, 2008 to 2024). A carcinoma that arises from epithelial cells of the prostate gland. "High expression of ACC1 protein in prostate cancer cells is caused by Pin1-mediated posttranscriptional level, contributing to increased FA contents that support cell proliferation." (PMID 38060103, 2023). "In support of this, a clinical study of nearly 600 prostate cancer patients, Pin1 was strongly associated with cancer severity and recurrence risk." (PMID 25588053, 2015). "In AD patient brain tissues, Pin1 expression is typically diminished, while in several cancer forms, such as prostate cancer, an increased expression of Pin1 is observed." (PMID 38544686, 2024). "This reaction at the key catalytic cysteine leads to an irreversible loss in Pin1 enzyme activity with treatment at high doses, decreasing Pin1 protein levels and suppressing cancer cell proliferation in breast, lung, and prostate cancers." (PMID 38745861, 2024). "By activating Wnt/β-catenin signaling, PIN1 has also been displayed to stimulate prostate cancer cell proliferation and migration." (PMID 37105032, 2023). "Similar to Pin1, these interactions lead to increased transcriptional activity of these receptors, which leads to cell proliferation in breast and prostate cancer." (PMID 37508437, 2023). "An in vitro protease-coupled assay on the prostate cancer cell line PC-3 showed that (S)-2 inhibited Pin1 and exhibited moderate cytotoxicity via suppression of CyclinD1 expression." (PMID 37508437, 2023). "They show that combining Pin1 inhibition with ralaniten compounds that bind to the AR N-terminal domain has enhanced antitumor activity on castration-resistant prostate cancer in xenografts, suggesting therapeutic potential." (PMID 33753863, 2021). "The levels of Pin1 protein were detected in all five of the human prostate cancer cell lines examined and were highest in androgen-sensitive LNCaP cells and lower in AR-negative PC-3 and DU145 cells." (PMID 33753863, 2021). "Using specific siRNA, Pin1-targeted inhibition suppresses transformed properties and prevents cell proliferation in prostate cancer cells." (PMID 32258027, 2020). "Especially compound 9a, one of the artemisinin derivatives increases anti-proliferative, pro-apoptotic and anti-metastatic effect in PC-3 prostate cancer cells by decreasing the expression of Pin1, cyclin D1, c-Myc, elF4E, and PCNA." (PMID 32258027, 2020). "Accordingly, Pin1 expression and tumor progression have also been positively correlated in brain, breast, cervical, colon, liver, and prostate cancers." (PMID 31884567, 2020). "The compound inhibited the activity of PIN1, to stabilize cyclin D1, which improved anti-proliferative effects of prostate cancer treatment through new mechanisms." (PMID 32258027, 2020). "hsa-miR-296-5p was shown to play a tumor-suppressive role by directly targeting Pin1 in prostate cancer." (PMID 30974831, 2019). "We found Pin1 expression levels to correlate positively with ACC1 levels in human prostate cancers, and we focused on the relationship between Pin1 and ACC1." (PMID 30899433, 2019). "Under hypoxic conditions, the hypoxia transcription factor HIF1α upregulates KLHL20, an E3 subunit, which promotes degradation of PML in a CDK2- and Pin1-dependent manner, thus promoting prostate cancer progression." (PMID 29416846, 2018). "More recently, miRNAs-miR-200c and miR-296-5p have been shown to inhibit PIN1 expression in breast and prostate cancer, respectively." (PMID 28076852, 2017). "A recent study reported that PIN1 expression is regulated by the tumor suppressive miRNA miR-296-5p in prostate cancer." (PMID 27258148, 2016). "Pin1 inhibition reportedly blocks the cell growth of prostate cancer cell lines, and Pin1 expression in prostate cancer is regarded as an independent prognostic marker." (PMID 26039047, 2015).
prostate carcinoma (continued). "On the other hand, Pin1 reportedly plays an important role not only in tumorigenesis but also in maintenance of the transformed phenotype in prostate cancer cells." (PMID 26039047, 2015). "While the expression of Pin1 is ubiquitous, previous reports have shown high levels of Pin1 expression in a number of human malignancies, including lung, breast, colon and prostate cancers." (PMID 26039047, 2015). "Consistently, studies have found that high PIN1 expression correlates with poor prognosis in patients with different types of cancer, including prostate cancer and esophageal squamous cell carcinoma." (PMID 25120724, 2014). "The peptidyl-prolyl isomerase Pin1 is over-expressed in several cancer tissues is a potential prognostic marker in prostate cancer, and Pin1 ablation can suppress tumorigenesis in breast and prostate cancers." (PMID 24416409, 2014). "Furthermore, Pin1 can interact with the N-terminal domain region of the androgen receptor in prostate cancer." (PMID 39624096, 2024). "In addition, the expression level of ACC1 positively correlates with prolyl isomerase Pin1 expression in human prostate cancer specimens." (PMID 38060103, 2023). "In addition, Smad3 linker phosphorylation reportedly enhanced cell motility via a Pin1-dependent mechanism in PC-3 human prostate cancer cells and normal murine mammary gland epithelial cells." (PMID 36549646, 2022). "Pin1 promotes E3 ligase KLHL20-mediated degradation of PML to enhance prostate cancer progression." (PMID 33807199, 2021). "The peptidyl-prolyl isomerase Pin1 is frequently overexpressed in prostate cancer." (PMID 33753863, 2021). "Therefore, upregulation of Pin1 promotes prostate cancer cell proliferation and migration through activation of Wnt/β-catenin signaling." (PMID 33807199, 2021). "It was also shown previously that miR-296-5p could act to suppress tumor growth, with the capability of inhibiting malignant transformations and progression by targeting Pin1, for example in prostate cancer." (PMID 34109978, 2021). "Studies of the roles of SPOP and PIN1 in prostate cancer stemness and progression have revealed that PIN1 is an upstream regulator of NANOG and also protects the latter from SPOP-mediated polyubiquitination and degradation, thus promoting NANOG-conferred cancer stemness features in prostate tumors." (PMID 32268506, 2020). "The PIN1-targeted RNAi has been proved to suppress prostate cancer in vitro and mice model." (PMID 32703934, 2020). "In addition, MIR296 targeting PIN1, another gene involved in tumor development, suppresses cell proliferation and growth in prostate cancer cells." (PMID 32582296, 2020). "RNA interference of Pin1 inhibits the angiogenesis as well as the growth of prostate cancer." (PMID 32258027, 2020). "In addition, juglone has also shown to reduce the prostate cancer cell growth by inhibiting PIN1 activity." (PMID 32258027, 2020). "In addition, in these malignant cells, Pin1 expression levels were also upregulated, suggesting that Pin1 upregulates the expressions of ACC1 protein in human prostate cancers." (PMID 30899433, 2019). "Accordingly, lipidomics analysis was performed to evaluate whether Pin1 impacts FA contents in prostate cancers." (PMID 30899433, 2019). "Thus, we investigated how Pin1 modulates the gene expressions in both androgen-dependent and androgen-independent prostate cancer cell lines using microarray analysis." (PMID 26039047, 2015). "Importantly, in a comprehensive study of over 2000 human tumors representing 60 types of cancer, Pin1 was found to be at least 10% overexpressed in 38 of the 60 tumor types, especially for breast, colon and prostate cancers." (PMID 25588053, 2015). "Pin1, one of the peptidyl-prolyl cis/trans isomerases, is reportedly overexpressed in prostate cancers and is considered to contribute to accelerated cell growth, which may be one of the major factors contributing to their androgen-independent growth." (PMID 26039047, 2015).
prostate carcinoma (continued). "Pin1 expression is positively correlated with tumor grade in human prostate cancer (PCa) and could be an independent prognostic marker for PCa progression." (PMID 24416409, 2014). "This post-phosphorylational modification can have profound effects on the stability, function and localization of the target protein Pin1 is overexpressed in a range of human cancers, and high Pin1 expression is found in common adenocarcinomas, such as breast, lung, colon and prostate cancers." (PMID 19077306, 2008). "Another small molecule inhibitor of PIN1, PiB, inhibited both SPOP-mediated NANOG degradation and stemness-associated spheroid formation in prostate cancer cells; the application of PIN1 inhibitors against prostate cancer with wild-type SPOP was suggested by the researchers." (PMID 32268506, 2020). "Notably, it was demonstrated that Pin1 associates with ACC1 but not with acetyl CoA carboxylase 2 (ACC2) in the overexpression system as well as endogenously in the prostate cancer cell line DU145." (PMID 30899433, 2019). "Pin1 reverses the inhibitory mechanism of PML-mediated suppression of HIF-1α-induced angiogenesis in clear cell renal cell carcinoma and prostate cancer." (PMID 33807199, 2021). "One of the reported inhibitors of PIN1, aetyl-11-keto-β-boswellic acid (AKBA) derivative has been shown to inhibit the growth of prostate cancer PC-3 (IC50 = 40 nM) and LNCaP (IC50 = 270 nM) cell lines." (PMID 32258027, 2020). "Phosphorylated Thr179-Pro motif of Smad2/3 interacts with Pin1 in a TGF-β-dependent manner, inducing migration and invasion via N-cadherin in prostate cancer cells." (PMID 32296699, 2020). "Despite Pin1-regulated gene expressions differing between these two prostate cancer cell-lines, LNCaP (androgen-dependent) and DU145 (androgen-independent), Pin1 inhibition suppresses the proliferation of both." (PMID 26039047, 2015). "Two prostate cancer cell-lines, LNCaP (androgen-dependent) and DU145 (androgen-independent), were treated with Pin1 siRNA and its effects on gene expressions were analyzed by microarray." (PMID 26039047, 2015). "Furthermore, Pin1 directly promotes TGF-β-induced migration and invasion in human prostate cancer cells." (PMID 33807199, 2021). "Moreover, KLHL20 coordinates with Pin1 and CDK1/2 to mediate hypoxia-induced PML proteasomal degradation, thereby potentiating multiple tumor hypoxia responses in human prostate cancer." (PMID 32296699, 2020). "In prostate cancer, tumor suppressor SPOP interacts with Nanog and promotes Nanog poly-ubiquitination and subsequent degradation, but Pin1 functions as an upstream Nanog regulator and impairs its recognition by SPOP, stabilizing Nanog to promote the cancer stem cell traits and tumor progression." (PMID 32296699, 2020). "Although we found that miR-296-5p also decreased PIN1 expression, as was previously reported in prostate cancer, there was no differential expression of miR-296-5p between HCC and the corresponding non-tumourous liver tissues." (PMID 28076852, 2017). "In this study, we used two prostate cancer cell line types, LNCaP which has an androgen dependent growth property, and DU145 which shows androgen independent growth, and compared the genes regulated by Pin1 between these two cell lines." (PMID 26039047, 2015). "Similarly, with the depletion of PIN1 by small hairpin RNA, the transforming growth factor (TGF)-β-mediated migration and invasion of human prostate cancer cells (PC3) were significantly inhibited." (PMID 24179535, 2013). "As an example, the gene PIN1, which is known to play a critical role in prostate cancer, has no overlapping direct neighbors in the two networks." (PMID 22568834, 2012). "There is interest in Pin1 as a potential prognostic marker for prostate cancer, but there are no reports on whether Pin1 expression in prostate cancer influences AR signaling." (PMID 33753863, 2021).
prostate carcinoma (continued). "However, genes of which the expressions are regulated by Pin1 have not yet been identified in prostate cancers." (PMID 26039047, 2015).
acute promyelocytic leukemia (21 papers, 2016 to 2025). An aggressive form of acute myeloid leukemia (AML), characterized by arrest of leukocyte differentiation at the promyelocyte stage, due to a specific chromosomal translocation t(15;17) in myeloid cells. "ATRA inhibits PIN1 and leads to its degradation, thereby destabilising PML‐RARα (aberrant promyelocytic leukaemia‐retinoic acid receptor α), to which PIN1 binds, and contrasting the proliferation of acute promyelocytic leukaemia cells." (PMID 34894990, 2022). "Although Pin1 is a key drug target for treating acute promyelocytic leukemia (APL) caused by a fusion oncogene, much less is known about the role of Pin1 in other heterogeneous leukemia." (PMID 29848341, 2018). "ATRA binds to the PIN1 active site and facilitates PIN1 degradation, resulting in suppression of acute promyelocytic leukemia cell growth." (PMID 26784107, 2016). "RARα forms driver fusion proteins in acute promyelocytic leukemia, for which Pin1 suppression is used as a treatment." (PMID 27540857, 2016). "We found that most of the differentially regulated phosphosites during OIS contained prolyl isomerase PIN1 target motifs, suggesting PIN1 is a key regulator of several promyelocytic leukemia nuclear body proteins, specifically regulating several proteins upon oncogenic Ras activation." (PMID 38216124, 2024). "Recently, it was reported that all-trans retinoic acid (ATRA), a therapeutic agent for acute promyelocytic leukemia, could inhibit and degrade Pin1 in cancer cells, which demonstrated a viable way for using Pin1 inhibitors as anti-cancer agents." (PMID 30934730, 2019). "In acute promyelocytic leukemia (APL), genetic or chemical inhibition of Pin1 can induce the degradation of the disease-causing fusion oncogene PML-RARα, which causes APL through blockage of promyelocyte differentiation and promotion of self-renewal capacity." (PMID 29848341, 2018). "All-trans retinoic acid (ATRA), approved by FDA for the treatment of Acute Promyelocytic Leukemia (APL), has been reported to be a potent PIN1 inhibitor." (PMID 36813923, 2023). "ATRA (tretinoin) is the only clinically used drug known to inhibit Pin1 and is FDA-approved to treat acute promyelocytic leukemia." (PMID 33753863, 2021). "As an alternative, we tested all-trans retinoic acid (ATRA), an agonist of the retinoic acid receptor (RAR) that is used medically to treat acute promyelocytic leukemia (APL) and was recently reported to inactivate Pin1 isomerase activity." (PMID 34535740, 2021). "Pin1 also stabilizes the oncogenic fusion protein PML-RARα, which disrupts the localization of wild-type PML from nuclear bodies to numerous micro speckles and induces a maturation arrest in promyelocytic leukemia." (PMID 33807199, 2021). "Unlike PiB and juglone, ATRA treatment in cells leads to the degradation of Pin1 and exhibits anti-cancer properties against TNBC and acute promyelocytic leukemia (APL); however, in TNBC mouse models, ATRA treatment showed only moderate antitumor activity." (PMID 38745861, 2024). "Another Pin1 inhibitor, all-trans retinoic acid (ATRA)—a commercially available drug used to treat acute promyelocytic leukemia (APL) and which both activates the retinoic acid receptor and inhibits the activity of Pin1—similarly reduced the proliferation of SARS-CoV-2." (PMID 34535740, 2021). "However, in a drug-repurposing effort, ATRA, an FDA-approved drug for the treatment of acute promyelocytic leukemia (APL), has also been shown to be a non-covalent Pin1 inhibitor." (PMID 37508437, 2023).
pancreatic cancer (18 papers, 2020 to 2025). "To ascertain that the plasma-stable agent 164B8 retained its ability to induce Pin1 degradation in cells, we tested it in three pancreatic cancer cell lines—human BxPC3 and MIA PaCa-2, and the mouse pancreatic cancer cell line KPC—using western blot analysis." (PMID 41322199, 2025). "Novel Pin1-degrading compounds were tested in a syngeneic mouse model of pancreatic cancer peritoneal metastases." (PMID 41322199, 2025). "Lastly, Pin1 has also been found to regulate the extracellular matrix composition and redox balance in pancreatic cancer through the NRF2/ARE pathway." (PMID 38727267, 2024). "Up-regulation of PIN1 in pancreatic cancer has been reported to activate NF-κB -IL-18 and stimulate the proliferation and invasion of cancer cells." (PMID 37105032, 2023). "Because our previous study found that PIN1 was closely related to the maintenance of redox balance in pancreatic cancer, we detected the level of reactive oxygen species (ROSs) in pancreatic cancer cells." (PMID 36834887, 2023). "The results showed that PIN1 protein expression was high in pancreatic cancer tissues with rich stroma, suggesting that deregulation of PIN1 in PDAC was closely related with tumor microenvironment." (PMID 36834887, 2023). "In this study, we detected the abundance of stroma in human pancreatic cancer tissues by Masson’s trichrome staining and detected the protein expression of PIN1 in tissues by immunohistochemical staining." (PMID 36834887, 2023). "A link between PIN1 and IL-1 cytokine family members has been identified in patients with pancreatic cancer." (PMID 35954317, 2022). "Further study on the mechanism of IL18 in PDAC showed that Pin1 promoted the proliferation and progression of pancreatic cancer cells by increasing the expression of IL-18 and continuously activating NF-kB cell pathway." (PMID 35464869, 2022). "Lianget al. reported that PIN1 transcriptionally activated NRF2 by interacting with c-Myc to bind to the promoter of NRF2 in pancreatic cancer." (PMID 35983979, 2022). "Functionally, antiCAFs-DMS selectively and drastically inhibited Pin1 in CAFs, resulting in higher cytotoxicity on CAFs than pancreatic cancer cells." (PMID 35879297, 2022). "Pin1 promotes pancreatic cancer progression and metastasis by activating the NF-κB-IL-18 feedback loop." (PMID 35783291, 2022). "Pin1 promotes IL-18-mediated tumor-promoting inflammation and pancreatic cancer progression in pancreatic ductal adenocarcinoma (PDAC) via upregulation of NF-κB signaling." (PMID 33807199, 2021). "Pin1 promoted pancreatic cancer cell proliferation, which was partially due to mitochondrial dysfunction, and Pin1 also maintained a redox balance via synergistic activation of c‐Myc and NRF2 to counteract Kras‐induced mitochondrial respiratory injury." (PMID 32347623, 2020). "Pin1 promoted pancreatic cancer cell proliferation and motility by increasing IL‐18 expression, while Pin1 knockdown also inhibited the tumour‐promoting effect of IL‐18." (PMID 32347623, 2020). "In agreement with our findings, other data proved that IL‐18 regulates NF‐κB signalling to implement its tumorigenic capacity, which supports the Pin1/NF‐κB/IL‐18 feedback loop in pancreatic cancer cells." (PMID 32347623, 2020). "In summary, our present study elucidated a novel regulatory mechanism for Pin1 via activation of NF‐κB‐mediated inflammation and the importance of Pin1 in oncogenic behaviour in pancreatic cancer cells." (PMID 32347623, 2020). "Our previous research showed the oncogenic role of Pin1 in supporting pancreatic cancer growth by maintaining redox balance via c‐Myc/NRF2 axis and highlighted it as an independent prognostic marker for PDAC." (PMID 32347623, 2020). "We performed wound healing and transwell assays to assess the role of Pin1 in pancreatic cancer cell motility." (PMID 32347623, 2020).